STAT6 (signal transducer and activator of transcription 6)
Diseases named in the same sentence as STAT6 in open-access papers (continued):
Sharing a sentence is not in itself a finding about the gene and the disease.
tumor (continued). "Indeed tumor STAT6 expression correlated strongly with an enhanced recurrence-free survival in a cohort of patients with head and neck cancer that had been treated with cisplatin-based chemoradiation." (PMID 22611421, 2012). "STAT3 and STAT6 are involved in inhibiting anti-tumour immunity." (PMID 21694723, 2011). "Similarly, it was found that in vivo inactivation of genes that govern MDSCs accumulation, such as STAT3 and STAT6 restores T cell function and promotes tumor regression." (PMID 21943203, 2011). "Moreover, platinum-based chemotherapeutics have been shown to downregulate PD-L2 expression in human dendritic and tumor cells via a STAT6-mediated mechanism." (PMID 22067141, 2011). "This would suggest that the potential benefits of STAT6 inhibition could be two-fold: enhanced anti-tumor immunity combined with growth inhibition and decreased invasive potential of the tumor cells." (PMID 21595984, 2011). "Furthermore, CD8+ T cells in STAT6-/- mice demonstrated enhanced levels of miR-17-5p expression when these mice bore B16 tumors compared with non-tumor bearing mice." (PMID 20167088, 2010). "Interestingly, not only are STAT6-/- T cells resistant to tumor-induced inhibition of miR-17-5p, but CD8+ T cells in tumor bearing STAT6-/- mice exhibited higher levels of miR-17-5p when compared with CD8+ T cells obtained from non-tumor bearing STAT6-/- mice." (PMID 20167088, 2010). "Similarly, it has been shown that several synthetic molecules (AS1517499, TMC-264, A771726) inhibited STAT6, one of the major signal transducers activated by IL-13 and involved in M2 polarization, leading to inhibited TAMs transformation and tumor progression in a mouse model of breast cancer." (PMID 40083710, 2025). "To assess whether STAT6 inhibition-induced iTregs (AS-iTregs) could exert excessive immunosuppression or promote tumor growth, we compared the effects of adoptively transferred control iTregs and AS-iTregs in the AOM/DSS-induced colitis-associated cancer (CAC) model." (PMID 41203944, 2025). "However, discrepancies between our results and previous studies suggest that the interactions between HPV oncogenes and STAT6 signaling may be more complex and variable, depending on the cell type, viral oncogene, tumor context, and viral load." (PMID 40733498, 2025). "Thus, STAT6 could be a potential therapeutic target for modulating immune responses and inhibiting tumor growth in PTC and HT patients." (PMID 40230479, 2025). "Consequently, we could conclude that the higher expression of STAT3, STAT4, STAT5A, STAT5B, and STAT6, the higher differentiation degree and less tumor stemness characteristics of BRCA tumor cells." (PMID 36968603, 2023). "Therefore, detection of STAT6-positive tumor cell nuclei would be useful for diagnosis of SFT." (PMID 37315497, 2023). "To determine whether the identified stroma-derived secreted factors contributed to STAT6 phosphorylation, we treated mutant desmoid tumor cells with recombinant secreted factors differentially expressed by the nonmutant cells and found that PTX3 induced the highest increase in phospho-STAT6." (PMID 37377751, 2023). "Likewise, STAT1 and STAT6 activation is also found to be closely related to tumor progression." (PMID 35740527, 2022). "Likewise, the medium and high doses of TAM significantly decreased the expression of p-JAK1 and p-STAT6 in the tumor tissues compared to that of the untreated control group, and the effect was stronger than that of TMZ, as detected by Western blotting and immune histology chemistry (IHC)." (PMID 35269804, 2022). "Thus, STAT6 is a potential therapeutic target for anti-tumor angiogenesis." (PMID 35600336, 2022). "Moreover, when tumor-bearing mice were injected with αGC, intratumoral DCs and iNKT cells showed less STAT6 phosphorylation and IFNγ production, respectively, than cells from the spleen, although similar production of IL4 was detected for the intratumoral iNKT cells and splenic iNKT cells." (PMID 31160756, 2020).
tumor (continued). "Thus, a decrease in STAT6 in the tumor stroma results in decreased Th2 cells." (PMID 33194642, 2020). "However, in the tumor microenvironment, activated Stat6 could directly mediate the transcriptional suppression of Trim24 in M2-polarized macrophages, in which low levels of Trim24 were insufficient to mediate CBP ubiquitination and Stat6 acetylation." (PMID 31554795, 2019). "However, the role of IL-4 in tumor growth under the condition of STAT6 inactivation is unclear." (PMID 31798581, 2019). "The tumour-bearing group had increased serum WF content, and the skeletal-muscle showed a reduction in IRS-1 and RAG activation, increased PKB/Akt and Erk/MAP4K3 on the 21st day, and maintenance of p70S6K1, associated with increases in muscle STAT-3 and STAT-6 levels in these tumour-bearing rats." (PMID 30975087, 2019). "Additionally drugs such as carboplatin, but not other chemotherapies, have been shown to downregulate the programmed death ligand 2 (PDL-2) on both dendritic cells and tumour cells, resulting in enhanced antigen specific T-cell activation, through the IL-4/STAT6 pathway." (PMID 29373959, 2018). "In addition, platinum-based chemotherapeutics not only stimulate class I HLA expression but also inhibit signal transducer and activator of transcription 6 (STAT6)-regulated expression of PD-L2, thus limiting immunosuppression by both dendritic cells and tumor cells." (PMID 27181838, 2016). "Thus, the targeting of BCL6 and STAT6 in addition or prior to the treatment with components of the current immuno-chemotherapy may sensitize the PMBL tumor cells for drug effects, at least in parts of PMBL cases." (PMID 25594020, 2014). "Ferulic acid suppresses tumor growth by inhibiting the PI3K/AKT and JAK2/STAT6 pathways, thereby promoting apoptosis (in vitro and in vivo)." (PMID 42193064, 2026). "The high stiffness of the tumour ECM activates Piezo1 in macrophages, triggering the STAT6/PPARγ signalling pathway, which promotes M2 polarization and suppresses anti-tumour immunity." (PMID 41437911, 2026). "Taken together, these findings suggested that irisin, OSM, and GEN can impede tumor progression and shift towards M2 macrophages by suppressing the JAK1/STAT6 pathway." (PMID 40604704, 2025). "The higher immunogenicity of TC was accompanied by the more profound expression of STAT6 and SMAD4 in tumor cells." (PMID 39936166, 2025). "We first examined the primary tumor cells that we profiled by ChIP-seq and retrieved a robust nuclear signal for NAB2 and STAT6." (PMID 40875449, 2025). "In our patient's case, the tumor's spindle-cell morphology and positive staining for CD34 and STAT6 confirmed the diagnosis." (PMID 40672405, 2025). "In this case, spindle and stellate tumor cells were strongly positive for vimentin and CD34, and negative for CK, desmin, SMA, HMB-45, MDM2, CDK4, p16, β-catenin, and STAT6." (PMID 41458523, 2025). "In vitro, BBR suppressed IL-4 or tumor cell supernatant-induced M2 polarization, as evidenced by decreased expression of M2 polarization marker genes (Arg1, Retnla, etc.)and reduced JAK1/STAT6 phosphorylation levels." (PMID 41585886, 2025). "In the B16 melanoma tumor model, STAT6 induces M2 macrophage polarization and inhibits TRIM24 expression in M2 macrophages, thereby inducing an immunosuppressive tumor niche." (PMID 40131539, 2025). "Future research should further explore the detailed mechanisms of STAT6 in PTC and HT, as well as its impact on the tumor’s immune microenvironment and therapeutic responses." (PMID 40230479, 2025). "P2X7 activation of STAT6/IRF4 drives M2 polarization, fueling tumor proliferation, angiogenesis, and T-cell suppression." (PMID 40079009, 2025). "Results showed that the expression levels of p-JAK1 and p-STAT6 in the tumor tissue of the sleep deprivation group were significantly upregulated, while ICI118,551 inhibited the expression of p-JAK1 and p-STAT6." (PMID 40276761, 2025).
tumor (continued). "Functionally, Stat6−/− macrophages lost the ability to suppress CD8+ T cell proliferation and to promote tumor cell migration in vitro." (PMID 40588561, 2025). "Exosomal miR-210 can be conveyed to endothelial cells, leading to facilitating tumor angiogenesis via targeting inhibition of sma and mad homolog 4 (SMAD4) and signal transducer and activator of transcription 6 (STAT6)." (PMID 41567219, 2025). "The patient underwent open complete resection of a giant abdominal pelvic tumor with no complications and was diagnosed as SFT according to the pathology, immunohistochemistry showed that the tumor tested positive for CD34(+), STAT-6(+), and Ki-67 (10%)." (PMID 39121255, 2024). "Among them, some transcription factors have been reported to mediate the EMT process, such as TBL1XR1, STAT6, ETV6, and SMARCA4, indicating their potential to regulate VM and promote tumor invasion." (PMID 38694917, 2024). "Immunohistochemistry showed that tumor tested positive for CD34(+), STAT-6(+), and Ki-67 (10%) and negitive for SMA, Desmin, S-100, EMA, DOG1, CD117, TLB1, CDK4, Pax-8, MDM2, Myogenin, and CD31." (PMID 39121255, 2024). "Immunohistochemical staining revealed that the tumor was positive for alpha-smooth muscle actin, but negative for CD34, desmin, keratin 18, S-100 protein, melan A, c-kit, and STAT6." (PMID 38805072, 2024). "We observed that iHSP110-33 reduced, in a dose-dependent manner, the phosphorylation of STAT6 in PMBL and cHL cell lines as well as in HEK293S6 cells and in vivo in K1106P tumor xenografts." (PMID 38773631, 2024). "In a murine model of colorectal cancer, activated STAT6 and KLF4 induced M2 polarization of TAMs, leading to tumor progression." (PMID 39516356, 2024). "In turn, tumor cell-derived IL-4 induces the activation of CAFs and stimulates POSTN expression by activating STAT6." (PMID 38773979, 2024). "The results showed that the presence of tumor-CM significantly increased binding of HES1, along with STAT6, to the Arg1 promoter, suggesting HES1 directly binds to the Arg1 promoter to lead its expression." (PMID 39702544, 2024). "In a delicate balance between immune regulation and achieving robust anti-tumor immunity after BMT, it is possible that STAT6-dependent gene expression can lead to diverse outcomes in different cells." (PMID 39796136, 2024). "Immunohistochemistry staining revealed diffuse positive expression of STAT6 and CD34 in the tumor cells." (PMID 38388450, 2024). "Cancer cells directly drive cholesterol efflux from macrophages and facilitate IL4-driven STAT6-dependent protumor TAM programming, while the deletion of ABC transporters reverts the tumor-promoting programming of TAMs." (PMID 39516356, 2024). "For in vitro experiments, a tumor-bearing mouse model was established, with which the CD206 level was detected by histochemistry, and the binding mode between GAN and STAT6 was simulated through molecular dynamics." (PMID 38244580, 2024). "The STAT6 dependency of the Treg-mediated separation of GVHD and GVT and the induction of expression of anti-tumor proteins remains to be established." (PMID 39796136, 2024). "Taken together, we concluded that a tumor sample with high STAT1, STAT2, STAT4, and STAT5B expression levels tended to be enriched in T cell dysfunction phenotypes, while STAT6 showed to be the opposite." (PMID 36968603, 2023). "The phosphorylation of STAT6, required for M2 macrophage polarization and pro‐tumor function, was decreased in macrophages incubated with the supernatant of USL‐treated tumor cells." (PMID 36479819, 2023). "Our prognostic signature consists of five genes, PYGB, IFNGR2, TICAM1, STAT6, and VPS4B, each of which plays a critical role in necroptosis and tumor progression." (PMID 36936916, 2023). "‐IL‐4‐mediated, STAT6/PI3K‐dependent, macrophage reprogramming, triggered by cholesterol efflux, led to increased arginine metabolism, that promoted immunosuppression and tumor growth." (PMID 36658699, 2023).
tumor (continued). "The results showed that the expression levels of PYGB, IFNGR2, TICAM1, STAT6 and VPS4B in CHOL tissues showed an overall upward trend compared with non-tumor hepatobiliary duct tissues." (PMID 36936916, 2023). "Surgical specimens revealed spindle tumor cells surrounding the mammary ducts and were immunoreactive for both CD34 and STAT6, suggesting SFTs." (PMID 37315497, 2023). "Lin found that miR-210 secreted by HCC cells can promote tumor angiogenesis by targeting SMAD4 and STAT6 to endothelial cells." (PMID 37914951, 2023). "Immunohistochemical staining revealed that the tumor cells were positive for CD34, CD99, Bcl-2, and STAT6." (PMID 37491539, 2023). "In mouse model of H22 tumor cells, lncRNA CENDE downregulated the expression of CD163, STAT-6, and VEGF by promoting M2 polarization, thus indirectly regulating tumor angiogenesis." (PMID 35145526, 2022). "Then, we confirm that nanoliposomes distribute to M2-TAMs in vivo and delivery of different compounds (STAT6 inhibitor (AS1517499), zoledronic acid or muramyl tripeptide) reduces the premetastatic niche and/or tumor growth in vivo." (PMID 35927238, 2022). "Immunohistochemistry staining (magnification, ×400) showed that the tumor cells were positive for CD34, STAT6, Ki67 (8%), CD99, and Vimentin." (PMID 36386546, 2022). "Tumor-infiltrated T helper 2 (Th2) cells produce IL-4 and IL-13 to activate Janus kinase 1 (JAK1)- signal transducer and activator of transcription 6 (STAT6)-MYC axis and enhance glycolysis, thus promoting tumorigenesis." (PMID 36230914, 2022). "To assess in more detail the impact of Stat6 knockdown on the TME myeloid compartment, we performed gene expression analysis using the NanoString platform in the pool of enriched tumor CD11b cells." (PMID 35179953, 2022). "In HT-1080 tumor cells, progesterone-induced blocking factor (PIBF) treatment increases STAT6 phosphorylation, and inhibition of PIBF with siRNA significantly reduces MMP2 expression." (PMID 35600336, 2022). "Tumor cells were positive with regard to the membranous and cytoplasmic expression of CD34, bcl-2, and CD99 and furthermore showed nuclear STAT6 positivity (respectively)." (PMID 36428694, 2022). "In the greatest number of tumors, STAT4 was correlated with tumor growth, then STAT1, STAT3, STAT6, STAT5B, STAT2, and STAT5A." (PMID 36176415, 2022). "The second type of signaling is mediated by factors produced by tumor stroma (the NF-KB Pathway, STAT1, STAT6)." (PMID 35359390, 2022). "As it is well known, the expression of SFT markers STAT6, CD34, CD99 and bcl-2 can be lost in most aggressive tumours, following a process of dedifferentiation." (PMID 35864381, 2022). "Next, to determine the effect of anti-inflammatory BDM, specifically, on tumour growth, myeloid specific deletion of KLF4 was used to suppress STAT6-mediated anti-inflammatory macrophage activation." (PMID 35359423, 2022). "During the tumor process, when the C-X-C motif chemokine receptor 2(CXCR2) is activated, the expression level of miR-449c targeting STAT6 mRNA in MDSCs is upgraded to promote the MDSC expansion." (PMID 35359390, 2022). "The secondary signals from tumor- and tumor stroma-derived factors including HMGB1, TLRs, TGFβ, and endoplasmic reticulum (ER) stress then pathologically activate MDSCs through STAT6, STAT1, and NF-κb signaling pathways." (PMID 36031601, 2022). "Anti‐Chi3L1 antibody treatment reduces M2 polarization with STAT6‐dependent PLG signaling, eventually reducing tumor growth and cancer metastasis." (PMID 34861103, 2022). "IL-4 and IL-13 are believed to carry out abundant functions in tumour cells through several pro-oncogenic pathways involving signal factors such as STAT3, STAT6, PI3K/Akt, and ERK1/2." (PMID 35409019, 2022). "Recently, we showed that targeting the STAT6 pathway with a small molecule, AS1517499, hampered M2 differentiation of TAMs and reduced M2 markers, and tumor migration." (PMID 35927238, 2022).
tumor (continued). "In contrast, STAT6 mediates the suppression of TRIM24 expression in M2 macrophages, contributing to the induction of an immunosuppressive tumor niche." (PMID 36577755, 2022). "Exosomal miR-210 derived from HCC cells is internalized by endothelial cells, and promotes tumour angiogenesis through direct inhibition of the SMAD4 (SMAD family member 4) and STAT6 (signal transducer and activator of transcription 6) genes." (PMID 34066780, 2021). "The results from FFPE tumor sample sequencing reveal a novel fusion transcript involving Nuclear Factor I X (NFIX), mapping to 19p13.2 and STAT6, mapping to 12q13.3." (PMID 34299133, 2021). "Exosomal miR-210-3p secreted by HCC tumour cells and delivered also in endothelial cells targeting SMAD4 (SMAD family member 4) and STAT6 (signal transducer and activator of transcription 6) resulted in enhanced angiogenesis." (PMID 34064331, 2021). "Immunohistochemistry testing for tumour characterisation showed hematopoietic progenitor cell antigen (CD34) and signal transducer and activator of transcription 6 (STAT6) positivity in keeping with an SFT." (PMID 34812333, 2021). "Careful examination of tumor for cases showing conventional SFT morphology along with diffuse and strong nuclear STAT6 expression leads to accurate diagnosis." (PMID 33879215, 2021). "EV-derived miR-210 released by hepatic tumor cells is transferred into endothelial cells and leads to tumor angiogenesis, inhibiting SMAD4 (mothers against decapentaplegic homolog 4) and signal transducer and activator of transcription 6 (STAT6) expression." (PMID 34207985, 2021). "Immunohistochemical staining revealed that the tumour cells were positive for CD34 and for signal transducer and activator of transcription 6 (STAT6)." (PMID 33781289, 2021). "The defective colonic inflammatory response observed in the STAT6−/− AOM/DSS mice at early stages of CAC, which is correlated with few tumor developments, led us to examine the local recruitment of Treg cells." (PMID 33919941, 2021). "In xenograft tumor tissues, the SCC-9-derived exosomes group exhibits highly expressed miR-29a-3p, lowly expressed SOCS1, and highly expressed p-STAT6." (PMID 34722637, 2021). "Histological features were evaluated and revealed a highly cellular tumor with positive expression of BCL2, CD34, CD99, and STAT6 proteins that are consistent with a diagnosis of SFT." (PMID 34765368, 2021). "Of pertinence, STAT6 has been described to act as a tumor suppressor in breast cancer, providing a possible mechanism-of-action of LINC01119/SOCS5 in driving TNBC cell growth by curtailing STAT6 activation." (PMID 34059683, 2021). "Compared with adjacent normal tissues, ITGA5, CD163, STAT6 and GATA3 levels were greater in most tumor tissues." (PMID 33711961, 2021). "Binding of IL-4 to IL-4 receptors on immune cells leads to STAT6 phosphorylation, nuclear translocation, and expression of GATA3 transcription factor, resulting in TH2 cytokine secretion and eventual tumor growth and metastasis." (PMID 34012451, 2021). "Immunohistochemically, the tumor cells exhibit strongly and diffusely positive cytoplasmic expression of CD34 and nuclear STAT6 expression; however, the expression of CD34 and STAT6 is frequently lost in dedifferentiated SFT." (PMID 32867125, 2020). "In the present study, we found that in the in vivo AOM/DSS CAC model, the inhibition of STAT6 phosphorylation by AS1517499 and the use of Trimethylglycine induced a remarkable reduction in tumor growth when they were administrated together with 5-FU." (PMID 32244885, 2020). "In a murine model of colorectal cancer, activated STAT6 and KLF4 are involved in MFHAS1-induced M2 polarization of TAMs leading to tumor progression." (PMID 32486098, 2020). "The progression-free analysis found that FAM90A1, ETS2, STAT6, MYT1L, ING2 and KCNK1 are related to tumour regrowth." (PMID 32015217, 2020).